PRC1 (protein regulator of cytokinesis 1)
Diseases named in the same sentence as PRC1 in open-access papers (continued):
Sharing a sentence is not in itself a finding about the gene and the disease.
tumor (continued). "The results of mice experiment demonstrated that knockdown of PRC1 could inhibit tumor growth." (PMID 33292244, 2020). "Moreover, our results suggest that the proliferative action promoted by CDK16 is mediated by PRC1, unveiling a new mechanism of PRC1 regulation that may contribute to tumor initiation and progression." (PMID 30992425, 2019). "In summary, this study demonstrates that PRC1 plays a crucial oncogenic role in NSCLC by driving cell division and tumor growth." (PMID 40665337, 2025). "Simultaneously, as a core component of PRC1, RNF2 can suppress the expression of tumor suppressor genes through histone modifications, thereby further driving tumor development." (PMID 40809844, 2025). "First, significantly higher staining intensities of phosphorylated PRC1, CCNY, and TET2 were detected in tumor tissues compared to normal tissues." (PMID 40665337, 2025). "Given that EZH2 is a key component of PRC2, targeting EZH2 has been proposed as a means to disrupt the cooperative action of PRC1 and PRC2, potentially restoring the tumor‐suppressive function of BAP1." (PMID 40904706, 2025). "In ovarian cancer, components of PRC1, including CBX proteins, contribute to disease development, recurrence, and chemoresistance by silencing tumor suppressor genes and regulating stem cell compartments." (PMID 40740235, 2025). "We then found from GEPIA database that PRC1 had a positive expression correlation with ICD markers (CRT and HMGB1) and the immune checkpoint gene CD274 in tumor tissues from COAD and READ patients." (PMID 40847353, 2025). "Using an external cohort, we show that the genes influencing OS within the signatures, such as FANCI and PRC1, are upregulated in CRC tumor vs. normal tissue." (PMID 39779996, 2025). "At the same time, proliferative markers such as MKI67, TOP2A, PRC1 and RRM2 underscore the importance of cell-cycle dynamics not only in tumor growth but also potentially within rapidly expanding immune subsets that contribute to treatment efficacy." (PMID 40745034, 2025). "These overexpressed tumor‐related genes such as tripartite motif‐containing 4 (TRIM4), protein regulator of cytokinesis 1 (PRC1), tubulin alpha 1b (TUBA1B), are closely related to inflammation and malignant differentiation." (PMID 38405061, 2024). "Highly expressed E2F3 in NPC cells activates transcription of PRC1 and BIRC5, which renders an immunosuppressive TME characterized by abundant M2 TAMs to trigger the growth and metastasis of tumor cells." (PMID 37647439, 2023). "However, although numerous accessory subunits of PRC1 are oncogenic, PRC1 exerts oncogenic functions not only by repressing tumor suppressors but also by activating oncogenes, so it remains to be explored whether PRC1 components are suitable therapeutic targets." (PMID 36076977, 2022). "Here, we show in the EwS model how uncoupling of mitosis and cytokinesis via targeting protein regulator of cytokinesis 1 (PRC1) or its activating polo-like kinase 1 (PLK1) can be employed to induce fatal genomic instability and tumor regression." (PMID 34531368, 2021). "A review of the literature found that six of the 12 upregulated genes (KPNA2, CDK1, TARBP1, PRC1, FEN1, and MCM6) were overexpressed in HCC tissue compared to levels in non-tumor tissue based on immunohistochemical staining." (PMID 32213663, 2020).
tumor (continued). "In vitro experiments have shown that PRC1 depletion inhibits the multiplication and invasiveness of NPC, while in vivo studies have found that PRC1 inhibits the neoplasia and radioresistance of NPC." (PMID 32863767, 2020). "Comparison of gene expression in TCGA cohort HCC samples also showed that PRC1 and TOP2A were significant up-regulation in HCC tumor tissues and up-regulation in advance tumor stage tumor tissues." (PMID 31737106, 2019). "Whereas, the expression of PRC1 and TOP2A in HBV-related HCC tumor tissue was markedly upregulated in the GSE14520 cohort, and also up-regulation in advance tumor stage samples." (PMID 31737106, 2019). "The expression of PRC1 and TOP2A also showed a strong correlation in HCC samples from TCGA (r = 0.922, P < 0.0001 for HCC tumor tissues, and r =0.842, P <0.0001 for adjacent normal tissues)." (PMID 31737106, 2019). "The results demonstrated that the mRNA expression of PRC1 was significantly induced in the LUAD tissues of these groups and positively correlated with the tumor, lymph node, metastasis (TNM) staging of LUAD." (PMID 30881920, 2019). "Here, the authors demonstrate that BMI1 directly interacts with AR leading to increased AR signaling independently of PRC1 complex and that targeting BMI1 inhibits tumor growth of castration-resistant prostate cancer tumors." (PMID 29402932, 2018). "p16INK4a, a known tumor suppressor which is epigenetically repressed by PRC2 and PRC1, can induce senescence and depletion of stem cells." (PMID 28445934, 2017). "It interacts with EZH2, SUZ12, and the PRC1 subunit CBX7 (ADP Ribosylation Factors) mediating the silencing of p16INK4a, p15INK4b and p14ARF tumor suppressors through the recruitment of PRC2 and PRC1." (PMID 26580594, 2015). "Here, we have identified multiple epigenetic regulatory networks, for example, the PRC1 complex, HP1γ, and BAF/Swi-Snf complex, which can contribute to the formation and maintenance of epithelial and mesenchymal tumor cell states." (PMID 25538889, 2014). "In subcutaneous xenograft tumor models in nude mice formed by H1299 cells, the intra-tumoral administration of Reb significantly suppressed tumor growth, reduced the staining intensity of KI67 and phos-PRC1, and enhanced the staining intensity of C-Cas3." (PMID 40665337, 2025). "Hence, the precise and dynamic balance between BAP1 and PRC1 is imperative for maintaining MHC-II gene expression and orchestrating the switch between the “hot” or “cold” status of tumor cells." (PMID 39817454, 2025). "Given their essential functions in PRC1 and EZH1, exploring their roles in inflammation and tumor progression could open promising avenues for therapeutic development." (PMID 40042761, 2025). "Moreover, GEPIA data indicated that PRC1 had a positive expression correlation with ICD markers, including CD274 (PD-L1), CALR (CRT), and HMGB1 in tumor tissues from COAD and READ patients." (PMID 40847353, 2025). "The expression level of PRC1 may serve as a predictive biomarker for the anti-tumor effectiveness of PLK1 inhibitors, further underscoring the importance of PRC1 research in clear ccRCC." (PMID 40093809, 2025). "Moreover, the ZFP36/PRC1 regulatory axis has been proposed as a potential therapeutic target, as restoring ZFP36 expression attenuates tumor proliferation and enhances chemosensitivity to agents such as 5-fluorouracil." (PMID 40361912, 2025). "Furthermore, the migrative and invasive phenotype of tumor cells, along with EMT, is reversed upon silencing PRC1." (PMID 38298209, 2024). "Next, we detected the levels of PRC1 and NUF2 through RT-qPCR, western blotting and Immunohistochemical, and found that the expression of PRC1 and NUF2 in the tumor tissues of the siRNA-Gm31932-174 treated group was significantly reduced, which reconfirmed the results of in vitro experiments." (PMID 35393397, 2022). "We also detected the role of PRC1 and RACGAP1 in tumor metastasis." (PMID 35445033, 2022).
tumor (continued). "Additionally, the expression of lncRNA-Gm31932, miR-344d-3-5p, PRC1, NUF2, cycle-related proteins, and Wnt/β-catenin pathway-related proteins in tumor tissues is consistent with the in vivo experiments." (PMID 35393397, 2022). "We find that the EwS-specific oncogenic transcription factor EWSR1-FLI1 hijacks PRC1, which physiologically safeguards controlled cell division, through binding to a proximal enhancer-like GGAA-microsatellite, thereby promoting tumor growth and poor clinical outcome." (PMID 34531368, 2021). "The results show that BIRC5, CENPA, KIF4A, DTYMK, PRC1, and TRIP13 have low beta values in tumor." (PMID 32391055, 2020). "The repression of ELOVL2 by the MYCN and PRC1 complex indicates PRC1 complex inhibition as a potential novel strategy to activate ELOVL2 tumor suppressive functions." (PMID 31856871, 2019). "In addition, the co-expression analysis performed by Pearson correlation also suggest that expression of PRC1 and TOP2A had a strong correlation (r = 0.798, P < 0.0001) in both HBV-related HCC tumor tissue and adjacent normal tissue (r =0.565, P <0.0001)." (PMID 31737106, 2019). "The tumor suppressive properties of DHA and ELOVL2 are repressed by the MYCN and PRC1 jointly, which suggests a new epigenetic mechanism of MYCN-mediated fatty acid regulation and indicates PRC1 inhibition as a potential novel strategy to activate ELOVL2 suppressive functions." (PMID 31856871, 2019). "Thus, while the roles of some PRC1 components in cancer seems mostly related to their requirement for stem cell survival, BCOR appears to be a bona fide tumor suppressor." (PMID 31123059, 2019). "In addition, differential analysis from the ONCOMINE online database of tumor and normal tissue in two cohorts indicated that ZWINT, PRC1, CDKN3, CDK1 and CCNA2 were highly expressed in ACC samples." (PMID 31572440, 2019). "ROC curve analysis indicates that PRC1 (P < 0.001, area under curve [AUC] = 0.976, 95%CI = 0.962-0.989) and TOP2A (P < 0.001, AUC = 0.978, 95%CI = 0.965-0.991) performed well in discriminate the HBV-related HCC tumor and adjacent normal tissue." (PMID 31737106, 2019). "Similarly, upregulation of a key subunit of the PRC1 complex, BMI1, has been shown to favor the reprogramming toward a CSC phenotype through the repression of tumor suppressor pathways in tumor-initiating cells." (PMID 30416982, 2018). "In sum, downregulation of PRC1 in OSCC could inhibit proliferation, subsequently leading to suppression of tumor growth in vivo." (PMID 29752448, 2018). "Notably, TOP2A and PRC1 were these 19 key prognostic genes, which were also identified as differential genes in the GSE40435 and GSE36895 datasets comparing paraneoplastic and tumor tissues." (PMID 40093809, 2025). "- miR-766-3p acts as tumor suppressor miRNA in HCC, maybe by targeting the Wnt3a/PRC1 pathway." (PMID 37205191, 2023). "Although other tumor suppressors may also be repressed by the PRC1 complex in the process of tumorigenesis, the oncogenic function of BMI1 and other PRC1 components has been mainly attributed to their repression of the cyclin-dependent kinase inhibitor 2A (CDKN2A) locus." (PMID 31211140, 2019). "Similar to the validation of survival analysis, ROC analysis of PRC1 (P < 0.001, AUC = 0.974, 95% CI = 0.958-0.990) and TOP2A (P < 0.001, AUC = 0.964, 95% CI = 0.944-0.985) in TCGA also performed well in distinguishing the HCC tumor and adjacent normal tissues." (PMID 31737106, 2019). "So, while overexpression of PRC1 components such as PCGF4/BMI1 might promote oncogenesis, it might also be a consequence of the proportion proliferating or stem like cells in the tumor, rather than a cause." (PMID 31123059, 2019). "Similarly, our data also confirms this notion that downregulated PRC1 also inhibits tumor growth without significant toxicity to the cells." (PMID 29752448, 2018).
tumor (continued). "Our findings show that CBX3, CBX4, and CBX8, all members of the polycomb (Pc) group of the non-canonical PRC1 (nPRC1) complex, are significantly upregulated in both CRC cell lines and tumor tissues." (PMID 40806514, 2025). "We investigated the expression of ASPM, CCNB2, CDCA5, KIAA0101, PRC1, and UBE2T in 12 LUAD tumor tissues and their adjacent non-malignant lung tissues." (PMID 33937050, 2021).
infection (13 papers, 2012 to 2025). The state of being infected such as from the introduction of a foreign agent such as serum, vaccine, antigenic substance or organism. "In contrast to PRC2, little is known about the recruitment and role of PRC1 factors on the KSHV genome following de novo infection." (PMID 36026503, 2022). "While viral lytic genes are transiently expressed after primary infection, their expression is significantly restricted and concomitant with the binding of host epigenetic repressors Polycomb Repressive Complex 1 and 2 (PRC1 and PRC2) to lytic genes." (PMID 36026503, 2022). "Based on our results we propose that RYBP uses a PRC1-independent mechanism to block KSHV RTA expression thereby promoting the establishment of KSHV latency following de novo infection." (PMID 36026503, 2022). "Using lentivirus-mediated infection, from cells expressing endogenous mCherry-PRC1, we generated cells also stably expressing ectopically EGFP-tagged central spindle protein CLASP1." (PMID 34580180, 2021). "Forty-eight hours after infection, both the mRNA and protein levels of PRC1 were significantly reduced in HepG2, Hep3B, and HuH-7 cells (P < 0.001), and a concentration-dependent knockdown efficiency by Ad-shPRC1 was observed." (PMID 29748662, 2018). "We show that both PRC2 and PRC1 are involved in the inhibition of lytic gene expression following de novo infection." (PMID 24367262, 2013). "Finally, also in accordance with previous findings, CerPrPSc in the brains of M-F1 and M-NO1 infected mice was relatively refractory to detection by mAb PRC1 compared with CerPrPSc generated by infection with North America CWD." (PMID 36692340, 2023). "Additionally, we found that the binding of RYBP and its effect on viral chromatin during de novo infection is PRC1-independent." (PMID 36026503, 2022). "Taken together, these results show that RYBP does not affect the chromatinization of viral promoters, the binding of RING1B or the deposition of H2AK119ub on viral promoters supporting our notion that the effect of RYBP on KSHV gene regulation during de novo infection is PRC1-independent." (PMID 36026503, 2022). "In addition, we have also demonstrated that while the PRC2-mediated H3K27me3-marked heterochromatin forms on the viral episome only after 24 hpi, the recruitment of the PRC1 factor RYBP already commences during the first hours of infection." (PMID 31923286, 2020). "However, the role and the mechanism of the recruitment of PRC1 factors during the first hours of infection are still unknown." (PMID 31923286, 2020). "Moreover, genes such as Cpz, Prc1, and Zgrf1, as well as metabolites like oleoyl-L-carnitine, 5-hydroxyindoleacetic acid, and CMPF, were underweighted in the DIABLO analyses but are associated with the infection process, highlighting their potential as biomarkers." (PMID 40475788, 2025). "The faster migration of CerPrPSc generated by infection with M-F1 and M-NO1 and its comparative resistance to detection by PRC1 results from PK cleavage downstream from the PRC1 epitope at residue 90 in both strains." (PMID 36692340, 2023). "During early infection, the E. chaffeensis tandem repeat protein 120 (TRP120) interacts with multiple PCGF isoforms, which are components of PRC1, degrading them and destabilizing the PRC1 complexes." (PMID 36293135, 2022). "We tested 7 distinct PRC1 factors during primary KSHV infection and found that each of them contributes to the downregulation of viral lytic genes to differing degrees during infection." (PMID 36026503, 2022). "Using lentivirus-mediated infection, cells stably expressing ectopically central spindle protein KIF4A-mGFP were generated from cells already expressing endogenous mCherry-PRC1." (PMID 34580180, 2021). "Taken together, our results indicate that LANA is required for the recruitment of both PRC1 and PRC2 onto the lytic KSHV promoters during de novo infection." (PMID 27606464, 2016).
infection (continued). "Here, we have found that the PRC1 complex is also recruited onto the KSHV genome and both PRCs are involved in the repression of lytic genes following de novo infection." (PMID 24367262, 2013). "The deposition of both repressive histone modifications, H3K27me3 and H2AK119ub, on the KSHV genome during de novo infection indicates that both PRC2 and PRC1 are recruited onto the viral episome." (PMID 24367262, 2013). "Thus, we confirmed that RYBP can function as a PRC1 factor on host promoters, but our results imply that RYBP functions differently on KSHV promoters during de novo infection." (PMID 36026503, 2022). "This non-canonical PRC1 recruitment can be mediated by transcription factors or epigenetic factors like KDM2B that can rapidly bind to the KSHV DNA during de novo infection." (PMID 31923286, 2020). "To directly compare de novo acquisition of PRC1- and PRC2-dependent marks on a global level, we performed ChIP-seq for H2AK119-ub, H3K27-me3 and H3K36-me2 in SLK cells after 24 hours and 5 days post of infection." (PMID 31671162, 2019). "We found that, during de novo infection, the binding of RYBP on the viral genome precedes that of EZH2, indicating a sequential recruitment of PcG proteins, where RYBP may recruit PRC1 independently of PRC2 at specific lytic promoters." (PMID 24367262, 2013). "This indicates that LANA may not directly recruit PRC1 onto the KSHV genome during de novo infection." (PMID 27606464, 2016). "However, the role of PRC1 factors in the repression of lytic genes following de novo infection has not been investigated, and thus their function during the establishment of KSHV latency is still largely unknown." (PMID 36026503, 2022). "To determine whether the observed, infection-dependent, increase in PcG immunofluorescence could be explained by an overall increase in protein expression, we next performed western blot analysis for the PRC2 proteins EZH2 and SUZ12 as well as the PRC1 proteins BMI1 and RING1B." (PMID 22279536, 2012). "We found that RYBP, a main subunit of the non-canonical PRC1 complexes, is a potent repressor of KSHV lytic genes that can bind to the viral genome and inhibit lytic genes as early as 4 hours post infection." (PMID 36026503, 2022). "To do so, we performed an shRNA screen in which we targeted 7 different PRC1 factors including canonical, non-canonical, and common PRC1 subunits during KSHV (BAC16-3xFLAG-RTA) infection." (PMID 36026503, 2022). "However, our recent study showed that KDM2B is not involved in recruiting PRC1 to KSHV lytic promoters and here we found that it also does not control RYBP binding to viral lytic promoters during de novo infection." (PMID 36026503, 2022). "Importantly, we found that the 3xFLAG-RYBP mutant that lacks only the 14-aa RBD still binds to KSHV lytic promoters during de novo infection as efficiently as WT RYBP, which confirms that the interaction of RYBP with PRC1 is not required for its binding to KSHV promoters." (PMID 36026503, 2022).